GPN1 (GPN-loop GTPase 1)
Description:
Small GTPase involved in the correct assembly of RNA polymerase II (RNAPII) complex, ensuring proper nuclear import of RNAPII. In vitro, exhibits a chaperone-like activity and a chaperone substrate protein can stimulate its GTPase activity. It is proposed to bind exposed hydrophobic peptide regions of newly synthesized RNAP II subunit, triggering the opening of a hydrophobic pocket in its GDP-bound state. This interaction likely traps exposed hydrophobic regions, preventing misassembly and providing a time window for association with the cognate RNAP II subunit. Peptide binding promotes GDP release, and increasing GTP affinity to facilitate GTP rebinding. Subsequent GTP hydrolysis would then lead to the release of the bound RNAP II subunit to enable association with cognate subunits and RNAP II assembly (By similarity). Forms an interface between the RNA polymerase II enzyme and chaperone/scaffolding proteins, suggesting that it is required to connect RNA polymerase II to regulators of protein complex formation. May be involved in nuclear localization of XPA.
Synonyms: MBDin; RPAP4; XAB1; NTPBP; ATPBD1A
Tractability: PROTAC: ubiquitination databases record sites on it; its protein half-life has been measured.
Gene: Protein-coding gene on chromosome 2 (27,628,247 to 27,651,511, forward strand). Ensembl gene ENSG00000198522.
Subcellular location: Cytoplasm; Nucleus
Subcellular location (Human Protein Atlas): Cytosol; Nucleoplasm; Mitochondria
Gene Ontology:
Molecular function: GTPase activity; protein binding; RNA polymerase II complex binding
Biological process: protein import into nucleus
Cellular component: cytoplasm; cytosol; nucleoplasm; nucleus
Genetic constraint (gnomAD): Loss-of-function variants: 6 observed, 8.2 expected, observed/expected ratio (o/e) 0.73, 90% interval 0.4 to 1.43. That is too few expected variants to judge how well the gene tolerates losing a copy. Missense variants: 123 observed, 112.85 expected, observed/expected ratio (o/e) 1.09, 90% interval 0.94 to 1.27. Synonymous variants: 66 observed, 45.55 expected, observed/expected ratio (o/e) 1.45, 90% interval 1.19 to 1.77.
Homologues: Orthologues: chimpanzee GPN1 (99% identical), macaque GPN1 (99% identical), pig GPN1 (93% identical), guinea pig GPN1 (91% identical), mouse Gpn1 (90% identical), rat Gpn1 (87% identical), rabbit GPN1 (79% identical), zebrafish gpn1 (78% identical), tropical clawed frog gpn1 (73% identical), Caenorhabditis elegans gop-2 (49% identical), Drosophila melanogaster CG3704 (47% identical). Paralogues in human: GPN2 (19% identical), GPN3 (19% identical).
Diseases named in the same sentence as GPN1 in open-access papers:
GPN1 is named in the same sentence as 21 diseases in open-access papers, as found by Europe PMC text mining. Sharing a sentence is not in itself a finding about the gene and the disease. The quoted sentences say what the papers report.
breast carcinoma (1 paper, 2025). "Meanwhile, the PrognoScan database revealed that patients with GBM, LUAD, breast cancer, and OV who had high levels of GPN1 expression also had a poorer prognosis." (PMID 39524004, 2025).
endometriosis (1 paper, 2025). The growth of functional endometrial tissue in anatomic sites outside the uterine body. "The role of “hubs” in these endometriosis-significant interactions was performed by proteins such as FNDC4 (participates in 9 pair interactions), NRBP1 and ZNF512 (7 pair interactions each), C2orf16, GPN1, and KRTCAP3 (6 pair interactions each)." (PMID 41373783, 2025).
esophageal carcinoma (1 paper, 2025). A primary or metastatic malignant neoplasm involving the esophagus. "The results showed that in esophageal carcinoma, HNSC, KIRC, KIRP, HCC, lung adenocarcinoma (LUAD), PAAD, thymic carcinoma, sarcoma, and uterine corpus endometrial carcinoma (UCEC), higher expression of GPN1 was associated with poor prognosis." (PMID 39524004, 2025).
glioblastoma (1 paper, 2025). The most malignant astrocytic tumor (WHO grade IV). "GPN1 protein levels were significantly different across several cancers, including glioblastoma (GBM), head and neck squamous cell carcinoma (HNSC), kidney renal clear cell carcinoma (KIRC), HCC, ovarian serous cystadenocarcinoma (OV), and pancreatic adenocarcinoma (PAAD)." (PMID 39524004, 2025).
hepatocellular carcinoma (1 paper, 2025). A malignant tumor that arises from hepatocytes. "To investigate the prognostic value of GPN1 in cancer and its role in the migration of hepatocellular carcinoma (HCC or LIHC) cells, we used several databases to assess GPN1 expression levels and effects in human tumors." (PMID 39524004, 2025).
Hypertension (1 paper, 2023). The presence of chronic increased pressure in the systemic arterial system. "rs2178197 (GPN1) was linked to hypertension, and hematologic traits." (PMID 37996473, 2023).
liver cancer (1 paper, 2025). An epithelial or non-epithelial malignant neoplasm that arises from the liver. "To further assess the prognostic significance of GPN1 in liver cancer, we analyzed the correlation between GPN1 expression and prognosis, including OS, disease-specific survival (DSS), and progression-free survival (PFS), using different datasets." (PMID 39524004, 2025).
oral cavity cancer (1 paper, 2021). A primary or metastatic malignant neoplasm involving the oral cavity. "rs3749147 was also correlated with waist circumference and triglycerides in the GWAS catalog and the GPN1 gene has been linked to oral cavity cancer, palmitoleic acid levels and periodontitis." (PMID 33563976, 2021).
renal papillary cell carcinoma (1 paper, 2025). "Based on data from the HPA database, GPN1 expression levels differ between normal and tumor tissues, specifically in kidney (renal papillary cell carcinoma, KIRP) and liver (HCC) tissues." (PMID 39524004, 2025).
cancer (3 papers, 2020 to 2025). A tumor composed of atypical neoplastic, often pleomorphic cells that invade other tissues. "In summary, our pan-cancer analysis, conducted through bioinformatics, explored the diagnostic and prognostic significance of GPN1 and demonstrated its role in HCC cell migration." (PMID 39524004, 2025). "Our genetic alteration analysis identified changes in the GPN1 gene across different cancers, primarily mutations and amplifications." (PMID 39524004, 2025). "The diagnostic value of GPN1 was evaluated using ROC curves across a variety of cancer types." (PMID 39524004, 2025). "Across multiple tumor datasets, and especially in HCC, GPN1 gene and protein expression were markedly increased, suggesting that GPN1 could serve as a potential diagnostic biomarker for various cancers." (PMID 39524004, 2025). "While GPN3 mutations are known to cause significant functional changes in various cancers, the expression, prognostic relevance, and biological function of GPN1 in human cancers—particularly in HCC—remain unclear." (PMID 39524004, 2025). "The results of this study suggest that GPN1 could serve as a valuable pan-cancer diagnostic and prognostic biomarker, based on its correlation with clinicopathological characteristics, tumor immune cell infiltration, and findings from functional enrichment analyses." (PMID 39524004, 2025). "Consistent with the TIMER2.0 findings, GPN1 expression was elevated in 13 cancer types but reduced in KICH." (PMID 39524004, 2025). "Based on GEPIA data, we identified the top 100 GPN1 co-expressed genes across pan-cancer types and performed GO and KEGG analyses." (PMID 39524004, 2025). "This study provides a comprehensive overview of GPN1 in human cancer and demonstrates that GPN1 contributes to the migration of HCC cells, potentially serving as a prognostic and immunotherapy biomarker." (PMID 39524004, 2025). "Our study found that GPN1 expression was significantly elevated in 19 out of 28 cancer tissue samples." (PMID 39524004, 2025). "GPN1 has emerged as a potential key player in cancer biology, influencing tumor progression, prognosis, and response to immunotherapy." (PMID 39524004, 2025). "According to the cBioPortal database, the GPN1 gene shows alterations across various cancers." (PMID 39524004, 2025). "The expression of GPN1 in 28 cancers in the TIMER2.0 database was analyzed." (PMID 39524004, 2025).
tumor (2 papers, 2025). "Additionally, GPN1 expression levels were associated with tumor infiltration status and response to immunotherapy." (PMID 39524004, 2025). "We found that the GPN1 gene and protein expression were significantly increased in several tumor tissues." (PMID 39524004, 2025). "Immunohistochemical (IHC) staining was conducted on tumor tissues and paired normal tissues to validate the differential expression of GPN1 at the protein level." (PMID 39524004, 2025). "Using publicly available data, we found that GPN1 expression differed significantly between various tumor types and normal tissues." (PMID 39524004, 2025). "Overall, these results suggest that GPN1 is involved in tumor immune infiltration and could serve as a potential biomarker to guide molecular targeted therapy and systemic immunotherapy in HCC." (PMID 39524004, 2025). "Nineteen tumor types showed a significant increase in GPN1 expression compared to the control group, while only kidney chromophobe (KICH) displayed lower GPN1 expression." (PMID 39524004, 2025).
GPN1 also shares sentences with these, for which no sentence is quoted: atherosclerosis (1 paper); head and neck squamous cell carcinoma (1); lung adenocarcinoma (1); oral cancer (1); ovarian serous cystadenocarcinoma (1); pancreatic adenocarcinoma (1); periodontitis (1); sarcoma (1); thymic carcinoma (1); uterine corpus endometrial carcinoma (1).